LEP (leptin)
Diseases named in the same sentence as LEP in open-access papers (continued):
Sharing a sentence is not in itself a finding about the gene and the disease.
colitis (continued). "Experimental colitis in rats resulted in elevated circulating leptin levels which correlate with the degree of inflammation and the development of anorexia and leptin antagonist ameliorated the development of chronic experimental colitis." (PMID 24877092, 2014). "In our study, leptin expression was increased in adipose tissue in both HFD groups compared to the colitis group." (PMID 22073943, 2011). "Utilizing the model of oxazolone-induced colitis, authors found that ob/ob mice were protected, whereas wild-type and leptin-reconstituted ob/ob mice developed colitis." (PMID 20808936, 2010). "Furthermore, the researchers established a T cell transfer model of colitis, which indicated that the stimulatory effects of leptin play a crucial role in this model, significantly delaying the onset of colitis." (PMID 40809439, 2025). "Previous studies have measured systemic leptin concentrations during acute experimental colitis." (PMID 40809439, 2025). "It has been found that the pubertal delay in male patients with colitis is accompanied by the decrease in fat stores, which leads to the decrease of leptin level, which may be one of the potential mechanisms." (PMID 35267960, 2022). "Accumulating evidence indicates a link between circulating leptin levels and colitis progression." (PMID 35888062, 2022). "Similarly, we demonstrated that the expression of leptin measured in both colonic mucosa and mWAT was significantly increased in colonic mucosa during experimental colitis." (PMID 33557311, 2021). "The expression of mRNA for adiponectin was significantly increased but the expression of leptin mRNA was significantly decreased in the mesenteric white tissue of the mice with TNBS colitis subjected to voluntary exercise as compared to the group maintained without voluntary exercise (p < 0.05)." (PMID 28425943, 2017). "Furthermore, we found that leptin, the product of adipose tissue, was increased in rats with colitis fed normal diet and this effect was markedly enhanced in rats fed HFD." (PMID 25684862, 2015). "Also, in rat model of experimental colitis, an elevated plasma leptin levels were observed which correlated with the degree of inflammation." (PMID 25684862, 2015). "In addition, a variety of agents such as FK506-entrapped nanoparticles, viral and nonviral NF-κB decoys, blockade of CD30-CD30L interaction, IL-25, leptin, and a plant-derived compound have been shown to ameliorate both colitis models." (PMID 24348533, 2013). "Leptin expression in adipose tissue was increased in both HFD groups compared to the colitis group." (PMID 22073943, 2011). "This may be due to increased leptin/Ob-R receptor binding because the receptor is overexpressed in inflamed colons of colitis animals." (PMID 22073943, 2011). "Therefore, we believe that leptin/receptor interactions in the colons of the colitis + HDF animals are partially responsible for maintaining local colonic inflammation." (PMID 22073943, 2011). "Previous evidence has shown thatthe expression of antimicrobial peptides and tight junction proteinsis increased in leptin-treated mice to ameliorate colitis, indicating that WEPE may improve intestinalhomeostasis by suppressing leptin resistance via the gut microbiota–brain–liveraxis." (PMID 38659208, 2024). "However, administration of leptin to ob/ob mice is able to revert their resistance to colitis." (PMID 33935782, 2021). "A similar trend was observed in our previous studies, which revealed that mice with colitis subjected to voluntary moderate training or forced moderate training had significantly elevated adiponectin plasma levels, while plasma concentrations of leptin, TNF-α, IL-6 and IL-13 were markedly reduced." (PMID 33557311, 2021). "Indeed, we found a reduction of leptin expression in the adipose tissue of colitis." (PMID 33110098, 2020). "Consequently, leptin deficiency protects mice against DSS- and TNBS-induced colitis." (PMID 31234447, 2019).
colitis (continued). "A recent study suggested that the protective effects of leptin on tight-junction proteins and mucosal barrier function in a DSS-induced mouse colitis model were partly mediated by STAT3 phosphorylation." (PMID 35888062, 2022). "Thus, the elevated leptin levels induced by HFD might be associated with the prevention of IEC apoptosis, which accounts in part for the protective effects of HFD feeding against DSS-induced colitis." (PMID 35888062, 2022). "LEP also plays a role in inhibiting NLRP3 inflammasome activation, ER stress, and oxidative/nitrosative stress in DSS-induced colitis." (PMID 33808793, 2021). "Plasma level of leptin was significantly elevated and the plasma adiponectin level was significantly decreased in animals with TNBS-induced colitis fed normal diet (P < 0.05) comparing with those measured in intact animals." (PMID 25684862, 2015). "We conclude that HFD delays the healing of colitis in trained rats via decrease in CBF and plasma IL-1β, TNF-α, TWEAK, and leptin levels and the release of protective irisin." (PMID 25684862, 2015). "Mesenteric adipose tissue from rodent colitis and Crohn's disease is metabolically active and shows inflammation-driven regulation of PPARγ, FXR and leptin." (PMID 21829567, 2011). "Additionally, both limonene and terpineol demonstrate anti-inflammatory effects by decreasing the levels of pro-inflammatory cytokines such as TNF, IL-6, leptin, and AOPP in a colitis induction model." (PMID 39456515, 2024). "Mechanistically, LEP treatment was found to block the activation of PPARγ/NF-κB and STAT3 pathways by upregulating PPARγ expression and retarding the phosphorylation of NF-κB p65, IκB, and STAT3 in DSS-induced colitis." (PMID 33981232, 2021). "Voluntary exercise, which failed to affect the leptin mRNA in adipose tissue of colitis mice fed SD, substantially decreased leptin mRNA expression in colitis mice fed HFD (p < 0.05)." (PMID 33557311, 2021). "To elucidate intrinsic leptin and LepR signaling in mucosal homeostasis, we exposed Leprdb/db and littermate control mice to DSS-induced colonic inflammation and examined them for sensitivity to colitis development." (PMID 33110098, 2020). "In contrast, the expression of mRNA for leptin was significantly increased in the sedentary mice fed a HFD as compared to the sedentary mice with or without colitis fed a SD (p < 0.05)." (PMID 28425943, 2017). "A further significant rise in the expression of leptin mRNA was recorded in the mice with colitis fed a HFD as compared to the values achieved in the sedentary mice without colitis fed a HFD (p < 0.05)." (PMID 28425943, 2017). "Exercise significantly decreased macroscopic and microscopic colitis, substantially increased CBF and attenuated the plasma TNF-α, IL-6, MCP-1, IL-1β and leptin levels while raising the plasma irisin and the plasma and WAT concentrations of adiponectin in HFD mice (p < 0.05)." (PMID 28425943, 2017). "In HFD animals, the exercise significantly accelerated the healing of colitis, raised the plasma levels of IL-6 and irisin, downregulated the expression of IL-1β, TNF-α, and Hif1α, and significantly decreased the plasma IL-1β, TNF α, TWEAK, and leptin levels." (PMID 25684862, 2015). "Macroscopic and microscopic colitis in sedentary SD mice was accompanied by a significant decrease in CBF, and a significant increase in the colonic expression of tumor necrosis factor-alpha (TNF-α), IL-6, IL-1β and leptin mRNAs and decrease in the mRNA expression of adiponectin." (PMID 33557311, 2021). "In contrast, the plasma levels of leptin were significantly raised in the sedentary mice without colitis fed a HFD, while a further significant increase in the plasma levels of leptin was observed in those with colitis fed a HFD (p < 0.05)." (PMID 28425943, 2017). "However, the higher circulating leptin concentration was seen only in the HFD group and not the Colitis + HFD group." (PMID 22073943, 2011).
Hypercholesterolemia (33 papers, 2011 to 2025). An increased concentration of cholesterol in the blood. "Female offspring of dams fed L-DE-71 (0.1 mg/kg/d) are susceptible to develop hypercholesterolemia, fatty liver, elevated plasma leptin and altered central markers of energy homeostatis relative to same-sex vehicle controls." (PMID 36277707, 2022). "L-DE-71 female offspring were particularly affected, showing hypercholesterolemia, elevated liver lipids and fasting plasma leptin as compared to same-sex VEH/CON, while L- and H-DE-71 male F1 only showed reduced plasma adiponectin." (PMID 36277707, 2022). "In conclusion, perinatal exposure to an environmentally relevant mixture/concentration of PBDEs during early life produces elevated fasting leptin, hypercholesterolemia and fatty liver in adult female offspring." (PMID 36277707, 2022). "The mechanisms are the increase of proinflammatory cytokines, sympathetic activity, oxidative stress, hypercholesterolemia, ghrelin, and the decrease of leptin." (PMID 35178257, 2022). "As a result of leptin resistance, obese Zucker rats exhibit a number of metabolic disorders similar to those seen in obese subjects, namely, hyperphagia, hypercholesterolemia, fatty liver and disorders within the distal intestine." (PMID 34686715, 2021). "Leptin administration within the subphysiological to physiological range dose-dependently reduces atherosclerotic disease indirectly by the attenuation of hypercholesterolemia and induction of adiponectin." (PMID 31500090, 2019). "It has been reported that simvastatin significantly increased insulin and leptin levels in patients with hypercholesterolemia." (PMID 24255692, 2013). "In the present study, we found a positive correlation of leptin with TC in men and a weak negative correlation with HDL-C in women, probably due to the higher prevalence of hypercholesterolemia and decreased HDL-C in men and in women, respectively." (PMID 24981337, 2014).
obstructive sleep apnea (33 papers, 2010 to 2025). "Serum leptin levels were associated with BMI in both patients with obstructive sleep apnea syndrome (OSAS) and normal controls." (PMID 35163627, 2022). "On the other hand, the increased prevalence of obstructive sleep apnea and high serum and CSF leptin levels in overweight patients may be another causal mechanism." (PMID 39154176, 2024). "Leptin has been found to be elevated in obese individuals and patients with obstructive sleep apnea." (PMID 20811596, 2010). "The aim of this study was to investigate the relationship among plasma leptin, ghrelin, adiponectin, resistin levels, and obstructive sleep apnea syndrome (OSAS)." (PMID 20835311, 2010). "It is believed that the elevated CRP levels in obesity and obstructive sleep apnea bind to leptin resulting in elevated serum levels." (PMID 20811596, 2010). "Some of these symptoms might be related to leptin, as a recent meta-analysis documented elevated serum leptin levels in patients with obstructive sleep apnea syndrome compared to controls." (PMID 37189804, 2023). "High leptin levels are common in obstructive sleep apnea syndrome patients." (PMID 36253984, 2022). "While endogenous leptin levels may provide cardioprotective effects against hypoxia, leptin resistance is common among obese individuals presenting with obstructive sleep apnea." (PMID 36160851, 2022). "Increased prevalence of obstructive sleep apnea (OSA) and elevated serum and CSF leptin levels among overweight patients might be another causative mechanism." (PMID 36127965, 2022). "Taken together, these data suggest that long-term exposure to CIH, as seen in obstructive sleep apnea, may contribute to a state of leptin resistance promoting an increase in body weight." (PMID 35153807, 2021). "This study also did not assess potential confounding factors such as emotional stress, elevated glucocorticoid levels, menstrual cycle phase, or the use of specific sleep medications for conditions such as obstructive sleep apnea, which may influence circulating leptin concentrations." (PMID 41439942, 2025). "However, a systematic review showed that improving obstructive sleep apnea with continuous positive airway pressure reduced leptin and ghrelin levels which could reduce food intake." (PMID 36349055, 2022). "In another study on patients with moderate-to-severe obstructive sleep apnea, CPAP therapy improve insulin secretion capacity; reduce total cholesterol, low-density lipoprotein and leptin levels." (PMID 35755912, 2022). "There is a potential link between leptin and obstructive sleep apnea, although the relationship is complex and not fully understood." (PMID 37834783, 2023).
eating disorder (32 papers, 2010 to 2025). A broad group of psychological disorders with abnormal eating behaviors leading to physiological effects from overeating or insufficient food intake. "Eating disorder psychopathology and in particular, the eating concern subscale were negatively associated with leptin concentrations but only in the combined sample of acute and recovered AN individuals." (PMID 40284205, 2025). "The association noted between serum leptin and eating disorder psychopathology supports recent arguments that hypoleptinaemia is a trigger not solely for the body size but also brain functioning." (PMID 40284205, 2025). "Over 30 years of research have demonstrated that mutations in the leptin-melanocortin pathway (LMP) cause various forms of eating disorders." (PMID 39237720, 2025). "Similarly, hypothalamic dysfunction has been implicated in eating disorders, particularly in cases of binge eating, where dysregulation of appetite-related hormones such as leptin and ghrelin may drive pathological feeding behaviors." (PMID 40365004, 2025). "Prolonged downregulation of leptin has been shown to be associated with several body systems, and a threshold for hypoleptinaemia of 4 ng/mL has been hypothesised, under which “entrapment” in the eating disorder may be triggered." (PMID 40284205, 2025). "Furthermore, leptin resistance in obese individuals is a potential cause of eating disorders." (PMID 32013093, 2020). "Multilevel linear mixed‐effects meta‐analysis model for blood leptin levels (in ng/mL) for different eating disorders." (PMID 39643920, 2025). "The central finding is a robust inverse association between plasma oxytocin and eating-disorder severity (EDE-Q global, r = –0.734, p < 0.001), alongside consistent positive associations for leptin and adiposity indices." (PMID 41356005, 2025). "Aspen and colleagues (2014) assessed interesting interactions between the appetite-regulating hormones ghrelin and leptin (which work in tandem to signal hunger and then promote satiety), disrupted sleep, and eating disorders." (PMID 33804974, 2021). "The eating disorder is predicted to increase with six DRGs, which are LEP, IL6, GCG, SERPINE1, TNF, and INS." (PMID 32753925, 2020). "Accordingly, the aim of this article is to review the current state of the art of leptin in relation to AN to provide the theoretical basis for the initiation of clinical trials for treatment of this eating disorder." (PMID 31156489, 2019). "As a secondary investigation, we hypothesised that leptin is positively associated with BMI and levels of body fat, and leptin and IGF-1 are associated with eating disorder psychopathology." (PMID 40284205, 2025). "For example, using a more diverse sample with wider body weight range may have made the linearity of the relationship between levels of leptin and eating disorder psychopathology more noticeable." (PMID 40284205, 2025). "BMI, presence of an eating disorder, leptin, adiponectin, BMD, vitamin D, lean mass, and fat mass were compared between those with and without AIS at ages 8, 10, 14, 17, and 20 years, and multiple logistic regression was performed between these variables and AIS." (PMID 38505221, 2024). "The role of leptin levels for risk of AN was previously hypothesized in a GWAS on stringently phenotyped patients with AN that provided hints for a dysregulation of leptin signaling in this eating disorder." (PMID 34594363, 2021). "Molecular studies support our findings in a biological context by suggesting atypical signaling from neuroendocrine factors of insulin, leptin, and ghrelin and corresponding gene expressions modulate perturbed inhibitory and reward systems, encouraging eating disorders." (PMID 32785278, 2020). "Furthermore, the observed correlations between oxytocin/leptin and eating behavior corroborate the hypothesis that probiotics may serve as modulators of both physiological and psychological aspects of eating disorders." (PMID 40732941, 2025).
eating disorder (continued). "Previous research similarly found a negative association between leptin and eating disorder psychopathology, which may be related to the role of leptin in reward circuits." (PMID 40284205, 2025). "In addition, leptin levels may trigger the reward-related behaviours and psychological processes which play a role in the maintenance of eating disorder symptomatology." (PMID 40284205, 2025). "We hypothesize that for unknown reasons the clinical symptomatology of a subgroup of patients with AN persists despite attainment of endogenous leptin levels well above those characteristic of the state of starvation, potentially entailing a prolonged entrapment in the eating disorder." (PMID 40616697, 2025). "Changes in CpG methylation levels in individuals with AN compared to healthy controls could affect expression of the STAT3 gene and therefore the leptin signaling pathway, leading to impaired regulation of appetite and energy balance and thus to metabolic or eating disorders." (PMID 38849516, 2024). "Moreover, the malfunction of signaling molecules in the CCK/SRC/PI3K cascade reaction with leptin/JAK2/PI3K/STAT3 signaling pathway may lead to eating disorders." (PMID 36359184, 2022). "In addition, assessment of biological mechanisms of hunger such as ghrelin and leptin hormones may further elucidate the relationship between food insecurity, hunger, and craving, eating disorders, and weight outcomes." (PMID 34501745, 2021). "At age 17, the multiple logistic regression model identified that every unit increase in the eating disorder questionnaire score increased the odds of AIS by 2.43 times (odds ratio, 2.43; 95% CI, 1.00–5.38; p = .04) when adjusted for serum leptin." (PMID 38505221, 2024). "Longitudinal studies simultaneously measuring leptin and SPX in eating disorders and adjusting for BMI and body fat mass are needed, to further investigate the relationship between SPX and leptin and the function of SPX in eating disorders." (PMID 36079049, 2022). "Since leptin resistance was observed at d28, we not discharged the contribution of this non-physiological phenomenon to eating disorders observed." (PMID 27479001, 2016). "On the other hand, there is no doubt that leptin plays an important role in AN, because leptin secretion is profoundly altered in this eating disorder." (PMID 23724144, 2013). "Moreover, increased levels of antibodies for a large number of hunger and satiety hormones including leptin, ghrelin, orexin, and alpha-MSH were found in patients with eating disorders, including patients with AN, and some of the antibodies even correlated with eating disorder symptom severity." (PMID 30809191, 2019).